VDR (vitamin D receptor)
Diseases named in the same sentence as VDR in open-access papers (continued):
Sharing a sentence is not in itself a finding about the gene and the disease.
infection (continued). "This example illustrates how interplay between innate and adaptive immunity cooperates to mount an appropriate response to infection through regulation of the VDR-system." (PMID 23785369, 2013). "The vitamin D3 receptor (VDR) expression was slightly elevated during both primary infection and reinfection (≈ 1.7 fold) compared to its respective controls." (PMID 21414188, 2011). "LXR/RXR activation was the only pathway stimulated during both primary infection and reinfection while the VDR/RXR activation pathway was stimulated only during reinfection." (PMID 21414188, 2011). "Although previous studies have identified certain polymorphisms in the ACE2, ADAM17, FURIN, IFITM3, and VDR genes associated with infection susceptibility to SARS-CoV-2, our findings did not reveal any such associations (data not shown)." (PMID 40296872, 2025). "Polymorphisms in immune-related genes (HLA, TLR, and VDR) may influence individual immune responses to MTB, leading to differences in the onset of infection between males and females." (PMID 40600152, 2025). "We plan to expand our research in this area to determine whether specific outcomes and VDR expression are influenced by the timing of the infection during pregnancy, or by disease severity." (PMID 39458089, 2024). "Through up-regulating Vitamin D Receptor (VDR) and CYP27B1, these receptors initiate a signal cascade converting of 25(OH)D to 1,25(OH) D. During infection, monocyte and macrophage functions are regulated by 1,25(OH)D binding to the VDR, influencing multitarget gene expression." (PMID 38845818, 2024). "While primary SARS-CoV-2 infection will continue to occur as calcitriol targets the post-entry steps of infection, the upregulation of LL-37 via the VDR pathway will subsequently prevent secondary SARS-CoV-2 infection among cells, resulting in an overall reduction of virus titre." (PMID 36986786, 2023). "At 24 h after infection, VDR expression was examined using western blot analysis." (PMID 37898650, 2023). "In theory, infection with HCMV might throw VDR and Snail expression in the placental trophoblast progenitor cells of pregnant mothers out of balance, resulting in complications for the fetus." (PMID 36146811, 2022). "Third, the detailed mechanisms of VDR genetic alterations in the pathogenesis of inflammation or infection remain largely unknown." (PMID 35242885, 2022). "In addition to VDR downregulation, we also found that its heterodimerization partner RXRα is reduced at late time points of infection." (PMID 36146811, 2022). "Furthermore, the infection significantly upregulated the expression of the VDR and CYP27B1 relative to uninfected macrophages, and this overexpression was not affected by high glucose concentrations." (PMID 35204769, 2022). "VD deficiency or lack of VDR results in intestinal microbiota dysbiosis, inflammation, and barrier impairment along with increased susceptibility to infection and mucosal damage as well as disease exacerbation." (PMID 35619956, 2022). "However, expression of its homolog Snail1 inversely correlated with Snail2 and VDR expression, as it was strongly upregulated during infection, especially on the protein level." (PMID 36146811, 2022). "We could reproduce this downregulation of Snail2 in infected HFF, but, surprisingly, its homolog Snail1 was strongly induced and inversely correlated with VDR expression throughout infection." (PMID 36146811, 2022). "However, little is known about how the intestinal VDR are involved in TJs and intestinal inflammation and infection, especially in in vivo systems." (PMID 35406694, 2022). "Such 3-day infection of A549 and monocytes/macrophages (acquired from A549) in cocultures allowed us to evaluate fast-acting innate immunity components including macrophage VDR-antimicrobial activities and γδ T-mediated antimycobacterial immunity in PBMCs." (PMID 34912331, 2021).
infection (continued). "Probiotics could increase VDR signaling and inhibit infection-induced inflammation in both human and mouse IECs." (PMID 34576700, 2021). "We therefore hypothesize that MIR337-3p not only could target/depress VDR antimicrobial response but also suppress fast-acting antimycobacterial immunity, leading to enhanced pathogenicity of infection." (PMID 34912331, 2021). "Similar to T helper cells, cytotoxic T lymphocytes (CTL) express both CYP27B1 and VDR, and upregulation of VDR can be observed in response to infection as well as mitogen stimulation, suggesting a coordinate regulation of VDR signaling pathway and CTL responses." (PMID 32679784, 2020). "Studies determining susceptibility for mycobacterial infections have identified host genetic factors that increase risk for these infections; examples are polymorphisms in the major histocompatibility complex, TLR, vitamin D receptor genes, genes encoding IFN-gamma signaling components and SLC11A1." (PMID 32033287, 2020). "Furthermore, the VDR gene, as part of innate immunity, is responsible for the prevention and elimination of infection and the determination of the gut microbiome." (PMID 32471257, 2020). "Except for Hsd3b1, infection with S. haematobium did not have an influence on Vitamin D pathway associated (VDR, Cyp27b1) or immunological (IL10, IFNG, Foxp3) genes as well as vitamin D plasma levels." (PMID 31673046, 2019). "However, VDR expression was significantly up-regulated following infection with leVDR lentiviral vector that efficiently generated VDR overexpression compared with empty control vector (leVDR vs leCtrl)." (PMID 29659618, 2018). "We then studied whether infection with uropathogenic E. coli could directly affect transcriptional activity of the VDR by employing a luciferase reporter assay in human bladder cells." (PMID 28749951, 2017). "Moreover, VDR is upregulated during infection in a toll-like receptor 2/1 (TLR2/1)-dependent manner." (PMID 28232830, 2017). "Frequency distribution of genotype and alleles of VDR and MBL-2 gene varies among different ethnic population, which may lead to variable susceptibility to the infection." (PMID 26693353, 2015). "Similarly, in PKDL, raised serum 25(OH)D3 was accompanied by an enhanced mRNA expression of CYP27B1, VDR and LL-37, indicating that infection upregulated the molecular switch needed for monocyte polarization towards a M2 phenotype." (PMID 26496711, 2015). "ChIP studies also revealed that infection enhances DNA binding by the VDR." (PMID 23762029, 2013). "The idea of vigorous VDR signaling in donors being favorable (as seen in the study of Bogunia-Kubik and colleagues) could suggest VDR mediated immune activation could promote more aggressive immune surveillance of infection and preclinical disease relapse." (PMID 23778150, 2013). "In addition, upregulation of VDR was previously reported following in vitro infection of macrophages with L. chagasi as well as L. donovani and L. major, suggesting that VDR is an important component of the host response to Leishmania infection." (PMID 24034621, 2013). "Although in experiments vitamin D inhibits plasmodium growth in vitro, in malaria infections neither VDR gene polymorphisms or vitamin D levels correlate with infection." (PMID 22242171, 2012). "In addition, TGR5, S1PR2, and VDR were the main BARs that have been affected by the infection." (PMID 39287458, 2024). "Infections related to SNPs in VDR have been described in other fields of medicine, which could be related to the presence of this receptor in lymphocytes and antigen-presenting cells for autocrine signaling through the production of active vitamin D metabolite." (PMID 39770689, 2024). "According to these findings, vitamin D levels and "ApaI" VDR gene polymorphisms could affect the parasite load and susceptibility to infection, whereas BsmI, FokI, and TaqI polymorphisms did not." (PMID 37319132, 2023).
infection (continued). "Additionally, viral transcription seemed to be necessary for VDR downregulation, since the infection with UV-inactivated HCMV incapable of immediate early transcription did not lead to reduced VDR levels at different time points throughout infection, as determined by Western blot." (PMID 36146811, 2022). "Therefore, we considered that during infection, active vitamin D might inhibit excessive ROS through the VDR-Bmi1 signaling pathway." (PMID 35957979, 2022). "Similarly, while large reductions were seen in the level of DENV genome in the supernatant (consistent with the plaque assay results), smaller, but still statistically significant results were seen in cells treated with all VDR agonists as late as 12 h post-infection." (PMID 32616772, 2020). "VDR is known to negatively regulate bacterial-stimulated NF–κB activity, and this mechanism may also be an important contributor to intestinal homeostasis and host protection from bacterial invasion and infection." (PMID 33396382, 2020). "Our results showed that the four VDR polymorphisms display similar frequencies across the non-infected, asymptomatic, and symptomatic dog groups, and no genetic association between these SNPs and disease/infection status were observed." (PMID 28611427, 2017). "In response to injury or infection, keratinocytes upregulate CYP27B1 and VDR, leading to increased local production of active vitamin D, which in turn induces CAMP expression, thereby strengthening cutaneous immunity." (PMID 40649943, 2025). "Treatment with calcifediol resulted in the reversal of these gene expression trends with an upregulation of CYP27B1 and VDR expression and downregulation of CAMP expression 24 h post-infection." (PMID 38732603, 2024). "At the 48 h post-infection time point, there was an increased relative expression of CYP27B1 and VDR (1.62 ± 0.32 and 1.27 ± 0.34, respectively) and a decreased relative expression of CAMP (0.29 ± 0.15)." (PMID 38732603, 2024). "The well-established roles of VD3 and VDR in immune modulation further highlight the importance of maintaining optimal VD3 levels for general health and infection resistance." (PMID 39475231, 2024). "Calcifediol treatment also reversed MAP effects at 48 h post-infection, with a decreased expression of both CYP27B1 and VDR and an increased relative expression of CAMP." (PMID 38732603, 2024). "Within hours of lytic infection, HCMV becomes resistant to vitamin D therapy in vitro by downregulating VDR." (PMID 39475231, 2024). "This study aimed to evaluate the vitamin D contribution in the expression of VDR and CYP27B1, involved in the conversion of an inactive to an active form of vitamin D in the infected macrophages using M. tuberculosis as an infection model." (PMID 35204769, 2022). "Here, we focus on the roles of VDR, ER, ERR, and PPAR in autophagic host defense against infection and discuss other NRs as links between autophagy and innate immunity during infection." (PMID 32867365, 2020). "Simultaneous infection of C3H10 T1/2 with SMAD3- and VDR-expressing lentivirus led to an elevation in RANKL expression." (PMID 28216630, 2017). "Clearly, in its mediation of immune signaling the vitamin D receptor appears to have an impact on immune reconstitution after HSCT and subsequent risks of infection, graft versus host disease, and graft versus disease effect." (PMID 23778150, 2013). "By the end of crisis, there was an almost complete recovery of RXR, FXR, and CAR to those levels induced by vaccination before infection, whereas PXR and VDR were significantly higher expressed." (PMID 19341445, 2009). "However, plaque assays conducted with PRV-QXX at different multiplicities of infection (MOI of 0.1 and 1) suggested that suppression of VDR expression detrimentally affected PRV proliferation." (PMID 39475231, 2024).
infection (continued). "VDR expression in Huh7 cells also increased with time in SARS-CoV-2 infected cells compared to mock-infected cells-a contrast to Vero E6, which reduces VDR expression with infection time." (PMID 36986786, 2023). "A lack of VDR regulation results in a stout increase of Claudin-2 at the mRNA and protein levels post-infection." (PMID 36678175, 2023). "Indeed, both VDR and CYP27B1 are expressed in almost all immune cells, and their expression is modulated by the presence of an infection." (PMID 35408981, 2022). "A significant increase in VDR was seen for MDMs not treated with vitamin D3 from each infection status group following in vitro MAP infection (P < 0.001)." (PMID 36275033, 2022). "We did, however, observe reduced VDR protein expression upon hMPV infection, which was dependent on viral replication as UV-irradiated hMPV did not suppress VDR protein expression." (PMID 29780383, 2018). "In this setting, 1,25(OH)2D3 is proposed to be less effective in the early stages of infection, where T cells are not chronically activated and therefore have lower levels of VDR expression." (PMID 29066221, 2018). "Altogether, our data supporting the notion that 1,25(OH)2D3-activated VDR is an epigenetic regulator and may inhibits synthesis of cytokines in MRSA-stimulated infection by restoring the global level of H3K9me3, a histone H3 mark for gene silencing." (PMID 24661536, 2014). "Finally, 1,25(OH)2D3-activated VDR, acting as an epigenetic regulator, inhibits synthesis of cytokines in MRSA-stimulated infection by restoring the global level of H3K9me3, a histone H3 mark for gene silencing." (PMID 24661536, 2014). "In comparison, infection of previously activated T cells with human immunodeficiency virus (HIV) led to upregulation of DNMT3B, increased promoter methylation of VDR (45–70%), and decreased VDR gene expression." (PMID 24808866, 2014). "In response to Listeria moncytogenes infection, VDR−/− mice were able to clear a primary or secondary infection, although kinetics was delayed in the absence of the VDR." (PMID 22412984, 2012). "Infection caused a transiently increased expression of RXR, FXR, CAR, PXR, and VDR in non-vaccinated mice, however, expression dramatically dropped during crisis on day 11 p.i." (PMID 19341445, 2009). "In the first experiment, Vero E6 and Huh7 cells were either mock infected with media or infected with SARS-CoV-2 and harvested at 6-, 24- and 48-h post-infection (hpi) to determine the baseline mRNA expression levels of VDR, 24(OH)ase, and LL-37 without calcitriol treatment." (PMID 36986786, 2023). "Additionally, VDR expression in the mid-ileum was investigated which revealed no variation in expression among infection status groups." (PMID 36816182, 2023). "Thus, the results above from in-depth mechanistic experiments demonstrated that MIR337-3p targeted/depressed upstream TLR4/MYD88 and STAT3 signaling and the downstream VDR antimicrobial pathways of CYP27B1/DEFB4A/CAMP, leading to an enhanced mycobacterial entry/infection and growth." (PMID 34912331, 2021). "Despite the downregulation of autophagy markers observed by 7 d post-infection, CYP27B1 and VDR were still significantly upregulated indicating that TLR8 is still sufficiently engaged at these late time posts post-infection in the absence of significant cytotoxic effects (P > 0.05)." (PMID 26115100, 2015). "The up-regulation of VDR by infection in non-vaccinated mice may thus represent an insufficient counter-regulatory response to protect liver tissue from excessive damages due to extreme up-regulation of iNOS producing high NO levels." (PMID 19341445, 2009). "This association of autophagy genes in QTLs along with the recent identification of VDR as a leading edge gene in a GSEA-SNP analysis in bovine JD, provides evidence that both pathways may also be involved in JD pathogenesis and their roles in infection should be investigated further." (PMID 34485444, 2021).
infection (continued). "Results showed that expression of both structural and non-structural proteins was largely completely absent when treatment occurred at an early time point in infection, although reduced protein expression could be observed in cells treated with the VDR agonists as long as 12 h post-infection." (PMID 32616772, 2020). "The discovery of the Vitamin D receptor (VDR) and cytochrome P450 27B1 (CYP27B1) enzyme expression on immune cells has driven exploration into whether the active metabolite of vitamin D, 1,25 dihydroxyvitamin D3 [1,25(OH)2D3] (VitD3), has immunoprotective properties in the context of infection." (PMID 32318074, 2020). "Next, we found that transcription of immediate early genes was necessary for HCMV-induced VDR downregulation, and IE2 overexpression in the absence of infection sufficed to increase levels of Snail1 and moderately reduce VDR in a cell line." (PMID 36146811, 2022).